EZH2 (enhancer of zeste 2 polycomb repressive complex 2 subunit)
Diseases named in the same sentence as EZH2 in open-access papers (continued):
Sharing a sentence is not in itself a finding about the gene and the disease.
cancer (continued). "Of note, many studies have uncovered a shared dependency of cancers with mutant SWI/SNF subunits on EZH2 activity." (PMID 39472584, 2024). "Inhibition of EZH2 activity alleviated intestinal inflammation in experimental mice and delayed the occurrence of colitis-related cancer." (PMID 38245781, 2024). "Efforts to inhibit EZH2 or modulate H3K27me3 removal are being explored as strategies to reactivate tumor suppressor genes and slow cancer progression." (PMID 39456545, 2024). "Recent studies have further established that EZH2 plays a pivotal role in regulating cancer cell metabolism, particularly glutamine metabolism, by inhibiting GLS activity." (PMID 39518098, 2024). "Overexpression of EZH2 is common in many cancer types because it is involved in cancer initiation, development and progression." (PMID 38299307, 2024). "EZH2 has been known to be significantly overexpressed in drug-resistant cancer cells of multiple myeloma, leukemia, breast, colorectal (CRC), prostate and ovarian tumours." (PMID 39703687, 2024). "Considering the role of EZH2 in cancer, numerous EZH2 inhibitors have been created, such as 3-deazaneplanocin A (DZNep) and GlaxoSmithKline 343 (GSK343)." (PMID 39204206, 2024). "High EZH2-scores correlated with increasing grading, pN-, and American Joint Committee on Cancer-stage." (PMID 40135141, 2024). "Recently, the role of EZH2 besides in cancer has been highlighted in different organs, including the liver." (PMID 39408226, 2024). "Due to the widespread tumorigenic role of EZH2 and its overexpression in various cancers, EZH2 inhibitors are being evaluated in many clinical and preclinical studies." (PMID 38333212, 2024). "Specifically, ARID1A interacts with EZH2 and antagonized EZH2-mediated IFN responsiveness in cancer cells." (PMID 38461299, 2024). "EZH2 has been identified as being overexpressed in various cancer types, including extranodal natural killer/T cell lymphoma (NKTL), where it plays a well-documented oncogenic role." (PMID 38785979, 2024). "In 2020, we combined chemical propionylation-based Kme1 enrichment and pan-antibody-based Kme2 and Kme3 enrichment to study lysine methylome features in wild-type and mutant Enhancer of zeste homolog 2 (EZH2) cancer cells." (PMID 38862432, 2024). "Correspondingly, EZH2 is overexpressed in SCLC compared to other cancers, and EZH2 inhibition is able to delay chemoresistance and synergize with chemotherapy." (PMID 39456533, 2024). "It has been established that a high level of EZH2 and activation of H3K27me3 is found in many cancer types and confers a significantly poor prognosis." (PMID 38886296, 2024). "EZH2 is frequently upregulated in cancer, and high EZH2 expression is correlated with aggressiveness and a worse prognosis." (PMID 38949020, 2024). "Upregulation of XIST was reported to be associated with overexpression of EZH2, a key component of PRC2, and to act as an adverse prognosis indicator of cancer in male and female patients." (PMID 39639337, 2024). "For instance, transcription factors E2F and NF-κB have been shown to induce EZH2 transcription in various cancer cells." (PMID 38339397, 2024). "Elevated EZH2 expression is evident in various cancers, making it a prospective target for cancer therapy." (PMID 38534385, 2024). "Emerging evidence indicates a significant role of lncRNA XIST/EZH2/Klf2 axis in promoting cell proliferation and cancer aggressiveness." (PMID 39639337, 2024). "Studies on EZH2-mediated epigenetic changes and subsequent transcription changes have led to the development of precise cancer medicines 23-26." (PMID 39513112, 2024). "In a study in gastric cancer, EZH2 was shown to bind to the p21 promoter region and mediate H3K27me3 modification, a process that resulted in silencing of p21 and induction of cancer cell proliferation." (PMID 38494860, 2024).
cancer (continued). "Collectively, these data from both pharmacological and genetic inhibition approaches demonstrate that EZH2 inhibition triggers viral mimicry in ATRT cancer cells." (PMID 39472584, 2024). "A multitude of epigenetic modifiers, such as DNMT inhibitors, HDAC inhibitors, and EZH2 inhibitors, have been developed for cancer prevention, treatment, and overcoming drug resistance." (PMID 38834851, 2024). "Studies indicated that AGAP2-AS1 epigenetically stifled ANKRD1 and ANGPTL4 through recruiting EZH2, thereby facilitating cancer proliferation and metastasis." (PMID 39124865, 2024). "EZH2 is an important key in the development and evolution of cancer and therefore a potential therapeutical target." (PMID 40135141, 2024). "Overactivation is observed in several cancers, and higher EZH2 activity is generally accompanied by a worse disease prognosis and a more aggressive phenotype." (PMID 38672463, 2024). "EZH2, which is activated in cancers, promotes the methylation of Smad3, facilitating the recruitment of Smad3 to SARA and Smad3′s subsequent activation by TβRI." (PMID 38675493, 2024). "One mechanism for such activation in cancers is through the histone methyltransferase EZH2 (enhancer of zeste homolog 2), a novel cancer therapeutic target." (PMID 38675493, 2024). "The regulatory effects of ncRNAs binding to EZH2 have significant therapeutic potential in different cancers." (PMID 38473229, 2024). "EZH2 has been shown to be crucial for the continued proliferation of in vitro cancer cell lines, and the ectopic expression of this protein can confer a proliferative advantage in primary cells." (PMID 39682746, 2024). "Increasing evidence links the impaired EZH2 function to the onset and progression of various cancers, such as prostate, bladder, colorectal, and breast cancers." (PMID 38476362, 2024). "The oncogenic dependence of cancer cells on EZH2 has sparked interest in it as a therapeutic target, leading to the development of several inhibitors." (PMID 39766049, 2024). "Of all the KMTs, EZH2 inhibitor are being tested to treat a series of cancers, and has come into phase III (NCT04224493) that will hopefully soon be available in clinical settings to help patients." (PMID 38172378, 2024). "PF-06821497, CPI-205, MAK683 and DS-3201 are other EZH2 inhibitors that are currently being studied in clinical trials on different cancer sub-types as a monotherapy or in combination with other therapeutics." (PMID 39703687, 2024). "The role of the PRC2 complex in cancer is complex, with the majority of studies suggesting that EZH2 promotes oncogenesis and is a pharmacologic cancer target." (PMID 39482699, 2024). "Novel studies have investigated the role of EZH2 as a prognostic factor and as a therapeutic target in multiple cancer entities including cSCC." (PMID 40135141, 2024). "Tazemetostat, a specific EZH2 inhibitor, has been granted accelerated approval by the US FDA for the treatment of SMARCB1-deficient cancers." (PMID 39472584, 2024). "The upregulation of EZH2 in both cancer cells and NK cells negatively affects this immune response in two different ways." (PMID 38254784, 2024). "This multifunctional role positions EZH2 as a significant player in diverse cellular processes, with implications for both normal physiology and pathological conditions, such as cancer." (PMID 39120328, 2024). "YTHDF1 promotes migration, invasion, and osteoblast adhesion and induces osteoclast differentiation of cancer cells in vitro and in vivo by inducing EZH2 and CDH11 translation." (PMID 39185313, 2024). "The EZH2 modulated metabolic activation can be targeted to synergize with EPZ-6438 in anti-cancer action." (PMID 37992808, 2024). "DAB2IP, known for its Ras-GTPase activity, suppresses cancer stem cell phenotype in several cancers, and its repression by EZH2 promotes cancer cell stemness." (PMID 39620228, 2024).
cancer (continued). "Drugs targeting AURKB, BCL-2, or EZH2 are currently in various stages of clinical development and have shown promising results for treating certain cancers." (PMID 38961535, 2024). "It has been reported that CDK1 promotes cancer cell migration and metastasis by phosphorylating proteins such as EZH2 and activating pathways such as Wnt/β‐Catenin and the ERK/GSK3β/SNAI axis." (PMID 38842135, 2024). "As a result, EZH2 stands as an essential therapeutic target in various cancers, prompting the testing of multiple EZH2 inhibitors in clinical or preclinical studies." (PMID 38333212, 2024). "Due to its significant involvement in cancer pathophysiology, EZH2 emerges as a prospective target for treating cancer." (PMID 38534385, 2024). "MYC was also proposed to cooperate with EZH2 or YY1 to repress the transcription of onco-suppressor genes in cancer while cooperating with YAP/TAZ mainly to enhance the transcription of oncogenes." (PMID 39455556, 2024). "When INI1 loses its regulatory function, EZH2 activity is up-regulated, allowing EZH2 to play a driving force of cancer development." (PMID 38434982, 2024). "These advancements in developing EZH2 inhibitors provide potential therapeutic strategies for various cancer types, offering new avenues for targeted treatment and potentially improving patient outcomes." (PMID 38600608, 2024). "EZH2-mediated epigenetic silencing of tumor suppressor genes leading to cancer proliferation has been reported earlier." (PMID 38473229, 2024). "One consistent downstream effect of EZH2 noted in other cancer types is the perturbation of the Wnt pathway." (PMID 38886296, 2024). "Suffice to say, our knowledge of EZH2 modulation of anabolic metabolic networks to influence cancer cell growth is still at its infancy." (PMID 37992808, 2024). "Down-regulation of EZH2 suppresses the growth and invasion in cancer cells, so we wanted to explore the relationship between EZH2 and H3K27me3 in the IL11/IL-11Rα pathway." (PMID 38886296, 2024). "Various EZH2 inhibitors have been formulated, and multiple clinical trials are ongoing to assess the effectiveness of drugs targeting EZH2 across diverse cancer types." (PMID 38534385, 2024). "To explore the mechanism of CENPA's influence on cancer, we searched for EZH2 as an upstream factor of CENPA." (PMID 39620895, 2024). "Enhancer of zeste homolog 2 (EZH2), the catalytic subunit of Polycomb repressor complex 2, is highly expressed in cancer stem cells of numerous malignant tumors and has a critical function in cancer stem cell expansion and maintenance." (PMID 39090713, 2024). "In vitro data demonstrate that small interfering RNA knockdown of EZH2 inhibits OS cell growth, proliferation, and invasion, and decreases cancer stem cell functions." (PMID 38886296, 2024). "EZH2, a significantly overexpressed oncogene across multiple cancer types, has emerged as a prominent target for cancer therapy." (PMID 38816356, 2024). "This molecular interplay between ERG and EZH2 underscores their importance in cancer progression and as targets for new therapies." (PMID 38216942, 2024). "This includes targeting specific vulnerabilities of SWI/SNF mutant cancers, such as the synthetic lethality observed with EZH2 inhibitors." (PMID 39471843, 2024). "In line with the known involvement of EZH2 in the invasion of cancer cells, EZH2 inhibition significantly reduced the invasion capacity of both the WT and the KO cells." (PMID 38672463, 2024). "Recently, the protective effect of EZH2 inhibition has been demonstrated, and various EZH2 inhibitors have been approved for clinical cancer treatments." (PMID 38169402, 2024). "Many studies indicate that the post-translational modifications of EZH2 play an important role in cancer development." (PMID 38346162, 2024).
cancer (continued). "In the realm of cancer development, enhancer of zeste homolog 2 (EZH2) serves as a crucial histone methyltransferase." (PMID 38678240, 2024). "EZH2 is considered as an important marker for the aggressive stages of prostate and breast malignancies due to its high expression levels in these cancers." (PMID 38346162, 2024). "Consequently, EZH2 inhibitor-resistant ARID1A-mutated cells become highly sensitive to BCL2 inhibitors like ABT263 suggesting that BCL2 inhibition alone or in combination with EZH2 inhibition represents an improved therapeutic strategy for ARID1A-mutated cancers." (PMID 39471843, 2024). "To this end, we combined the EZH2 inhibitor GSK126 with a panel of 20 existing anti-cancer compounds, that are under preclinical investigation or are already being used in the clinic, targeting prominent oncogenic signalling pathways." (PMID 38519707, 2024). "The role of EZH2 in cancer progression is increasingly recognized, with its heightened expression observed in various malignancies." (PMID 39565059, 2024). "Clinical trials are underway for multiple EZH2 methyltransferase inhibitors, and recent studies have shown that AMPK agonists hold promise as sensitizers for EZH2-targeted cancer therapy, enhancing the efficacy of EZH2 inhibitors." (PMID 38834851, 2024). "Previous reports have shown that DNMT1, together with EZH2, contributes to the transcriptional repression of the miR-200 family members, and EZH2 depletion reduces DNMT1 presence on the miR-200b/a/429 promoter in cancer cells." (PMID 38890707, 2024). "Targeted EZH2 inhibitors are currently under investigation for the treatment of cancers with SWI/SNF complex protein abnormalities such as SMARCA4-UT." (PMID 38903719, 2024). "This study underscores the necessity for personalized treatment strategies, including targeted therapies such as EZH2 inhibitors and immune checkpoint blockade, to address the unique molecular pathways in SMARCB1-deficient cancers." (PMID 39125735, 2024). "Another study demonstrated that EZH2-mediated methylation of SMAD3 at K53/K333 can drive cancer metastasis." (PMID 38834851, 2024). "On the other hand, Myc, deregulated in over 50% of human cancers, serves as a potent transcription factor governing cellular processes and contributing to tumorigenesis; Myc activates EZH2 expression and induces global gene expression." (PMID 38534385, 2024). "Recent evidence points to an important role of EZH2 in promoting tumorigenesis and progression by reprogramming cancer cell metabolism." (PMID 37992808, 2024). "Extensive studies have revealed that EZH2 is overexpressed in various malignancies and acquires gain-of-function mutations in subtypes of lymphomas, highlighting an oncogenic role for EZH2 in cancer progression." (PMID 39472584, 2024). "Reversible transition between the epithelial and mesenchymal states vertebrate carcinoma cell dissemination, and inhibitors of the PRC2 catalytic subunits EZH2 are currently being developed to treat several types of carcinomas as main or adjuvant therapy." (PMID 39174513, 2024). "Previous studies have shown that FGFR4 and EZH2 inhibitors can induce cell apoptosis in various cancer cells." (PMID 37085881, 2023). "In contrast, EED inhibitors still show efficacy in suppressing the proliferation of these cells, suggesting the potential advantage of EED inhibitors for treating SAM-competitive EZH2 inhibitor-resistant cancers." (PMID 37909018, 2023). "Accordingly, numerous studies have highlighted the role of EZH2 in cancer development and progression." (PMID 38146588, 2023). "EZH2 inhibition led to impaired proliferation of several human cancer cell lines with mutant SWI/SNF genes including BRG1 (SMARCA4), PBRM, and ARID1A." (PMID 38275587, 2023).
cancer (continued). "Various pathways have been implicated in cancer tumorigenesis, cancer cell proliferation, migration and invasion, including regulation of the miR-329-3p/ALDOA axis, modulation of the miR-101/EZH2 axis, modulation of the miR-411-3p/HOXA10 pathway, and others." (PMID 38203269, 2023). "EZH2 methyltransferase, for example, showed a mean mRNA z-score of 1.37 in basal cancers and 0.29 in claudin-low cases (t test corrected for multiple comparisons, p = 0.001)." (PMID 37504297, 2023). "The present study aims to elucidate how EZH2 affects the development and progression of various human cancers." (PMID 36545914, 2023). "Recently, because interest in epigenetic regulators for cancer treatment is increasing, EZH2 as the only epigenetic enzyme was selected in 23 transcription factors that satisfy all conditions." (PMID 36808829, 2023). "Various studies have been conducted to indicate EZH2 involvement in different cancers' progression and metastasis." (PMID 37940644, 2023). "Unlike RUNX1, which is frequently mutated in human cancer, the RUNX3 gene is often transcriptionally silenced in cancer by CpG island DNA methylation or through EZH2-dependent H3K27me3 (histone H3 lysine 27 trimethylation) modification in the RUNX3 promoter." (PMID 37190015, 2023). "It has been demonstrated in human tissues and murine models of different cancers, that EZH2 can increase and maintain Tregs stability by suppressing FOXP3 function." (PMID 37325482, 2023). "In comparison to the NC group, the nude mouse cancer volume in the EZH2-OE group increased remarkably (r<0.05)." (PMID 38048186, 2023). "Overall, our findings provide insight into the mechanism that drives the anti-cancer effect of the EZH2/RA single agent and combination treatment, and the effect determined by the presence of the fusion oncogene." (PMID 37858275, 2023). "Taken together, our findings provide a novel therapeutic strategy for TNBC and other EZH2 transcriptional activity dependent cancers." (PMID 36642705, 2023). "Retrieving the immune-TME and TNBC aggression-associated marker genes from the Pan-cancer TCGA-dataset, we found a high positive correlation of the expression of S100A9 and S100A8, two immune suppression marker genes, with AURKA and EZH2 in the TNBC samples." (PMID 37189841, 2023). "Given the pleiotropic role of EZH2 in cancer, it is imperative to develop a clear understanding of the mechanisms of EZH2 activators or inhibitors and to develop methods to increase the efficiency of these drugs." (PMID 38036730, 2023). "The scientific literature has put forward that KMTs inhibitors, especially EZH2 ones, either alone or in combination with other anti-cancer agents reduce the proliferation of prostate tumors." (PMID 37228649, 2023). "Expression of its catalytic subunit EZH2 correlates with cell proliferation, and its aberrant overexpression is frequent in many types of cancer cells." (PMID 37842084, 2023). "It has been reported that EZH2 phosphorylation at T487 in mouse suppresses histone methylation activity in differentiated mesenchymal stem cells and decreases cancer cell invasion." (PMID 37325482, 2023). "Use of EZH2 inhibitors in various potentially GD2-positive cancers such as neuroblastoma and Ewing sarcoma led to increased GD2 expression through upregulation of ST8SIA1, and in some cases B4GALNT1." (PMID 37670947, 2023). "The correlation between the EZH2 gene and cell invasion and metastasis of cancer is a research hotspot." (PMID 36672374, 2023). "The function of EZH2 participates in a heavy role in the regulation of genes during biological development, especially in cancer, where abnormal performance is often observed." (PMID 37689710, 2023).